OR51E2 (olfactory receptor family 51 subfamily E member 2)
Description:
Olfactory receptor. Activated by the odorant, beta-ionone, a synthetic terpenoid. The activity of this receptor is probably mediated by G proteins leading to the elevation of intracellular Ca(2+), cAMP and activation of the protein kinases PKA and MAPK3/MAPK1. Stimulation of OR51E2 by beta-ionone affects melanocyte proliferation, differentiation, and melanogenesis. Activation of OR51E2 by beta-ionone increases proliferation and migration of primary retinal pigment epithelial (RPE) cells. Activated also by the short-chain fatty acids (SCFA) acetate and propionate. In response to SCFA, may positively regulate renin secretion and increase blood pressure. May also be activated by steroid hormones and regulate cell proliferation. Activated by L-lactate in glomus cells (By similarity).
Synonyms: PSGR; HPRAJ; OR51E3P; OR52A2
Tractability: Small molecule: a structure with a bound ligand is known; it belongs to a druggable protein family. Antibody: UniProt places it where antibodies can reach, with high confidence; its Gene Ontology location is reachable by antibodies, with high confidence; UniProt predicts a signal peptide or a membrane-spanning region. PROTAC: a small molecule that binds it is known.
Target class: Family A G protein-coupled receptor; Membrane receptor
Gene: Protein-coding gene on chromosome 11 (4,680,171 to 4,697,854, reverse strand). Ensembl gene ENSG00000167332.
Subcellular location: Cell membrane; Early endosome membrane
Pathways (Reactome):
Sensory Perception: Expression and translocation of olfactory receptors; Olfactory Signaling Pathway
Gene Ontology:
Molecular function: G protein-coupled olfactory receptor activity; nuclear steroid receptor activity; olfactory receptor activity; signaling receptor activity; G protein-coupled receptor activity
Biological process: adenylate cyclase-activating G protein-coupled receptor signaling pathway; cell migration; detection of chemical stimulus involved in sensory perception of smell; melanocyte differentiation; melanocyte proliferation; steroid hormone receptor signaling pathway; cellular response to fatty acid; positive regulation of blood pressure; positive regulation of renin secretion into blood stream; cellular response to lipid; G protein-coupled receptor signaling pathway; nuclear receptor-mediated steroid hormone signaling pathway; system process
Cellular component: early endosome membrane; plasma membrane; membrane
Genetic constraint (gnomAD): Loss-of-function variants: 14 observed, 15.03 expected, observed/expected ratio (o/e) 0.93, 90% interval 0.61 to 1.45. The upper end of that interval is the gene's LOEUF score, 1.45, which puts it in group 6 of 6, group 1 being the genes least tolerant of losing a copy. Missense variants: 483 observed, 437.27 expected, observed/expected ratio (o/e) 1.1, 90% interval 1.02 to 1.19. Synonymous variants: 180 observed, 166.92 expected, observed/expected ratio (o/e) 1.08, 90% interval 0.95 to 1.22.
Homologues: Orthologues: chimpanzee OR51E2 (99% identical), macaque OR51E2 (99% identical), guinea pig OR51E2 (93% identical), rabbit OR51E2 (93% identical), rat Olr59 (93% identical), dog OR51E2 (93% identical), mouse Or51e2 (93% identical), pig OR51E2 (91% identical), tropical clawed frog or51ao2 (54% identical). Paralogues in human: OR51E1 (57% identical), OR51D1 (56% identical), OR51G2 (52% identical), OR51I2 (52% identical), OR52L1 (48% identical), OR51A4 (48% identical), OR52K1 (48% identical), OR52K2 (48% identical), OR51C1 (48% identical), OR52A1 (48% identical), OR52M1 (48% identical), OR51A2 (47% identical), and 39 more.
Diseases named in the same sentence as OR51E2 in open-access papers:
OR51E2 is named in the same sentence as 19 diseases in open-access papers, as found by Europe PMC text mining. Sharing a sentence is not in itself a finding about the gene and the disease. The quoted sentences say what the papers report.
prostate carcinoma (56 papers, 2005 to 2025). A carcinoma that arises from epithelial cells of the prostate gland. "OR2T6 is overexpressed in breast cancer tissues, whereas OR51E2 is overexpressed in prostate cancer and enhances tumor cell invasiveness via PTEN loss." (PMID 36779496, 2023). "The survival analysis revealed that progress-free interval is closely associated with the expression level of CENPF, TOP2A, and OR51E2 in the prostate cancer cohort." (PMID 36937411, 2023). "Analysis of a dataset from The Cancer Genome Atlas using GEPIA2 confirmed that OR51E2 and OR51E1 were significantly overexpressed in prostate cancer tissues, with OR51E2 being the more deregulated of the two." (PMID 40588561, 2025). "OR51E2 was among the most differentially expressed olfactory receptors in human prostate cancer, as demonstrated by analyses of data from The Cancer Genome Atlas." (PMID 40588561, 2025). "In human prostate cancer tissues, palmitic acid bound to olfactory receptor 51E2 (OR51E2) expressed by TAMs, enhancing their protumor phenotype." (PMID 40588561, 2025). "BI can inhibit the proliferation and migration of melanoma cells by activating OR51E2 and can inhibit the proliferation of prostate cancer cells by down-regulating cell cyclin-related proteins." (PMID 39241034, 2024). "For instance, OR51E2, was discovered in prostate cancer cells and named ‘prostate-specific G-protein-coupled receptor (PSGR)’." (PMID 38607054, 2024). "β-Ionone stimulation robustly activated ERK1/2 in HEK293 cells expressing FLAG-OR51E2, suggesting that, similar to endogenous OR51E2 in prostate cancer cells, exogenous FLAG-OR51E2 is fully capable of activating ERK1/2 in HEK293 cells." (PMID 36313302, 2022). "The olfactory receptor OR51E2 is ectopically expressed in prostate tissues and regulates prostate cancer progression, but its function and regulation in oncogenic mitogen-activate protein kinase (MAPK) activation are poorly defined." (PMID 36313302, 2022). "In this study, we have demonstrated that ectopically expressed OR51E2 is a potent activator of the MAPKs ERK1/2 in prostate cancer cells." (PMID 36313302, 2022). "In summary, we have demonstrated that ectopically expressed OR51E2 is a potent activator of the MAPKs ERK1/2 in prostate cancer cells and that the function of OR51E2 in activating ERK1/2 is mediated through a specific GA-localized Gβγ-PI3Kγ-ARF1 pathway." (PMID 36313302, 2022). "The purposes of this study are to characterize the function of ectopically expressed OR51E2 in ERK1/2 activation and to elucidate the possible underlying molecular mechanisms in prostate cancer cells." (PMID 36313302, 2022). "Although this is the first study on OR51J1, studies on OR51E2, another member of this family, which is expressed in melanoma and prostate cancer revealed that its activation via its ligand, β-ionone, inhibits cancer cell proliferation." (PMID 33566867, 2021). "OR51E1, a paralog of OR51E2, is also demonstrated to be functionally expressed in prostate cancer cells." (PMID 34452275, 2021). "OR51E2 is expressed in prostate epithelial cells, and expression is significantly increased in prostate intraepithelial neoplasia and prostate cancer relative to healthy tissue and benign prostatic hyperplasia." (PMID 34545457, 2021). "The activation of OR51E2 in prostate cancer, by its ligand b-Ionon, leads to decreased cell proliferation and migration." (PMID 33566867, 2021). "Recent studies have also identified genes for potential ORs as alternative genes for the treatment of cancer, including OR51E2, which is involved in the regulation and proliferation of prostate cancer." (PMID 34573430, 2021).
prostate carcinoma (continued). "OR51E2 activation results in anti-proliferative effect and metastasis in prostate cancer cells, anti-proliferative effect and melanogenesis in melanocytes and proliferation and metastasis in retinal pigment epithelial cells." (PMID 33321809, 2020). "Studies showed that β-ionone inhibits the proliferation and induced invasiveness of prostate cancer cells via activation of OR51E2, whereas β-ionone mediated-activation of OR51E2 inhibited proliferation and migration of melanocytes and induced melanogenesis." (PMID 33321809, 2020). "In fact, OR51E2 and OR51E1 have been established as prostate specific G-coupled receptor PSGR and PSGR2 among prostate cancer cells and are associated with tumor progression, cancer cell invasiveness and metastasis." (PMID 31551495, 2019). "Recently, OR51E2 [prostate-specific G-protein coupled receptor (PSGR)] was found to be overexpressed in prostate cancer tissues, and it accelerates prostate cancer development together with the loss of PTEN in a mouse model." (PMID 31781505, 2019). "Olfactory receptor OR51E2, also known as a Prostate Specific G-Protein Receptor, is highly expressed in prostate cancer but its function is not well understood." (PMID 29892571, 2018). "OR51E2 is known to function as a biomarker for prostate cancer, and its paralog, OR51E1, was discovered as a potent biomarker for the small intestine and some types of lung cancer." (PMID 29497600, 2018). "This was first observed in prostate cancer, where activation of OR51E2 by its ligand β-Ionon leads to diminished cell proliferation and migration." (PMID 29867524, 2018). "PSGR/OR51E2 has been shown to play a role in inhibiting proliferation of prostate cancer cells, a function that is thought to involve activation of TRPV6 and Pyk2." (PMID 30542293, 2018). "We previously reported that the olfactory receptor OR51E2, overexpressed in LNCaP prostate cancer cells, promotes cell invasiveness upon stimulation of its agonist β-ionone, and this phenomenon increases metastatic spread." (PMID 29084601, 2017). "The activation of OR51E2 was reported to inhibit the proliferation of prostate cancer cells, while overexpression promoted the tumour development." (PMID 28387360, 2017). "OR51E2 is involved in the regulation of cell growth, migration and the invasiveness of skin melanocytes, melanoma cells and prostate cancer cells." (PMID 29249973, 2017). "The odorant receptor 51E2 (OR51E2), which is well-characterized in prostate cancer cells and epidermal pigment cells, was identified for the first time as the most highly expressed OR in human fetal and adult retinal pigment epithelial (RPE) cells." (PMID 29249973, 2017). "In prostate cancer cells, OR51E2 activation leads to the opening of the transient receptor potential vanilloid type 6 channel via a member of the src kinase family." (PMID 29249973, 2017). "Some ORs show tumor-specific regulation, as shown for PSGR (OR51E2), which is highly expressed in prostate cancer cells but weakly expressed in normal prostate cells." (PMID 28273117, 2017). "Our previous studies investigated the role of the OR OR51E2, also named PSGR for prostate specific G protein-coupled receptor, which is overexpressed in LNCaP prostate cancer cells." (PMID 29084601, 2017). "For example, in the development of cancer diagnostics, OR51E2 has been described as a potential biomarker for the identification of prostate cancer due to its upregulation in prostate carcinoma cells compared to healthy prostate epithelial cells." (PMID 28174521, 2017). "In prostate cancer cells, OR51E2 activation results in an activation of protein tyrosine kinase 2 beta (Pyk2), which in turn leads to the phosphorylation of p38 mitogen-activated protein kinases." (PMID 29249973, 2017).
prostate carcinoma (continued). "The few studies investigating their function show that the activation of human ORs leads to, for example, secretion processes or influences the cell proliferation such as OR51E2 in prostate cancer cells or in melanocytes." (PMID 29249973, 2017). "A reduced proliferation rate, as a result of OR51E2 activation, was observed in melanocytes, melanoma cells and prostate cancer cells." (PMID 29249973, 2017). "In this context, the activation of OR51E2 by its specific agonist β-ionone leads to the inhibition of prostate carcinoma cell proliferation." (PMID 28174521, 2017). "We further assess this result using LNCaP prostate cancer cells, which overexpress an OR, the PSGR (also named OR51E2), described as a prostate tumor marker." (PMID 24416348, 2014). "Perhaps most interestingly, an olfactory receptor over-expressed in prostate cancer, OR51E2, interacts with androstenone derivatives and this interaction regulates cell proliferation." (PMID 22824328, 2012). "Importantly, immunofluorescence analysis of human prostate cancer sections confirmed that OR51E2 is expressed by tumor-infiltrating macrophages." (PMID 40588561, 2025). "Notably, OR51E1 (olfactory receptor E1 belonging to family 51) and OR51E2 (olfactory receptor E2 belonging to family 51) are known to be upregulated in prostate cancer tissues." (PMID 40588561, 2025). "Validation in plasma samples from prostate cancer patients and cancer-free individuals underscored the diagnostic and prognostic relevance of two genes, OR51E2 and SIM2, along with two miRNAs, miR-200c and miR-200b, in distinguishing prostate cancer presence with notable sensitivity and specificity." (PMID 38542382, 2024). "In this regard, the human ortholog OR51E2, sharing 93% identity with Olfr78, was recently detected in human pulmonary neuroendocrine cells and reported to activate a neuroendocrine phenotype in prostate cancer cells." (PMID 38177905, 2024). "Although there is no previously known involvement of olfactory genes in lymphoid cancers, these genes have been studied in other neoplasms such as prostate cancer; for instance the activation of OR51E2 facilitates the cellular transformation of the disease into a more aggressive form." (PMID 37379307, 2023). "Many lines of evidence suggest that OR51E2 could be utilized as a potential target for prostate cancer treatment." (PMID 34452275, 2021). "Among them is OR51E2, which is ectopically expressed in melanocytes as well as in primary melanoma and melanoma metastasis and whose activation has been shown to elicit an onco-suppressive effect in prostate carcinoma." (PMID 31337866, 2019). "The role of ORs in the prostate (and, most often, prostate cancer) has also been investigated in several studies, many of which focused on “prostate-specific G-protein-coupled receptor” (PSGR), another name for OR51E2, which has been referenced several times above." (PMID 30542293, 2018). "OR51E2/PSGR has been shown to inhibit the growth of prostate cancer cells." (PMID 30542293, 2018). "Due to their specific expression patterns, some ORs could moreover serve as tumor biomarkers, such as OR51E1 and OR51E2, in prostate cancer, lung cancer and small intestine cancer and OR7C1 as a marker of cancer-initiating cells in colorectal cancer." (PMID 29867524, 2018). "Moreover, the regulation of migration and invasiveness via OR51E2 was described in melanoma and prostate cancer cells." (PMID 29249973, 2017). "The most studies on OR51E2 have been focused on its pathophysiological functions and these studies have demonstrated that it regulates prostate cancer cell proliferation, invasion and migration, and prostate cancer progression and can be used as a prostate cancer biomarker." (PMID 36313302, 2022). "In an attempt to identify ligands that engage OR51E2 in human macrophages, we performed a lipidomic analysis of supernatant from the PC3 prostate cancer cell line." (PMID 40588561, 2025).
prostate carcinoma (continued). "Relevant to our goal of olfactory diagnosis of prostate cancer, we note that homologs of human olfactory receptors OR51E1 and OR51E2 are overexpressed in human prostate cancer tumor tissue." (PMID 40445905, 2025). "The boxplot demonstrated that SLPI is down-regulated in prostate cancer patients, while the CENPF, TOP2A and OR51E2 are up-regulated in prostate cancer patients compared with the normal cohort." (PMID 36937411, 2023). "A number of GPCRs, including OR51E2 and CXCR4, are over-expressed in prostate cancer patients and regulate prostate cancer cell growth, migration and invasion, and prostate cancer progression." (PMID 36313302, 2022). "Altogether, these data demonstrate a signaling pathway to mediate ERK1/2 activation by OR51E2 in which Gβγ translocation to the GA induces the activation of PI3Kγ and ARF1, and the GA provides a spatial platform in prostate cancer cells." (PMID 36313302, 2022). "Interestingly, identification of biologically relevant ligands for OR51E2, which was also found to be a key marker for prostate cancer, revealed that out of the 2500 virtually screened and subsequently 55 experimentally validated compounds, several endogenous compounds could activate OR51E2." (PMID 33807994, 2021). "OR51E2 and OR51E1 show an increased expression in prostate cancer cells, whereas OR51E1 is postulated to be a marker for lung cell carcinoids and cancer of the small intestine." (PMID 29497600, 2018). "The list of 10 genes again included the well-established prostate cancer markers KLK2, KLK3 (PSA), FOLH1 (PSMA), PSGR (OR51E2), STEAP2, NKX3.1 and Prostein), and also included NCAM2, SPON2 and HOXB13." (PMID 15583692, 2005). "Collectively, our data demonstrate that OR51E2 activates ERK1/2 through the Gβγ-PI3Kγ-ARF1 pathway that occurs spatially at the Golgi, and also provide important insights into MAPK hyper-activation in prostate cancer." (PMID 36313302, 2022). "For example, OR51E2, which contains an isoform including the 5′ UTR exon from OR51C1P, is highly expressed in prostate epithelium and has been identified as a biomarker for prostate cancer." (PMID 32126975, 2020). "Indeed, OR51E2 and OR51E1 have been reclassified in human prostate cancer cells as prostate specific GPCRs (PSGR and PSGR2 respectively)." (PMID 31551495, 2019). "Although the exact function of the receptor in prostate cancer has not yet been clarified, these data indicate the importance of OR51E2 in the pathogenesis of prostate cancer and OR51E2, and its ligand may be a new target to better combat prostate cancer." (PMID 34545457, 2021).
melanoma (8 papers, 2017 to 2024). A malignant, usually aggressive tumor composed of atypical, neoplastic melanocytes. "In particular, OR51E2 serves as a potential biomarker for melanoma." (PMID 35805166, 2022). "The previous study identified that human melanoma expresses the olfactory receptor 51E2 and further showed that activating endogenous OR51E2 in cultured cells isolated from metastatic and vertical growth phases can suppress the growth of melanoma via inducing apoptosis." (PMID 35805166, 2022). "Melanoma cells express the receptor OR51E2, which is upregulated in these cells in comparison to normal melanocytes, indicating that OR51E2 might play a role in early melanoma development and progression." (PMID 29497600, 2018). "In addition, OR51E2 was also identified in epidermal melanocytes and derived melanoma cells, in which the activation of OR51E2 affects cell-type specific physiological processes, such as pigmentation and proliferation." (PMID 29249973, 2017). "Furthermore, the function of OR51E2 is investigated in human melanoma cells: activation of OR51E2 by its ligand β-ionone inhibits the growth and migration of cells derived from vertical-growth phase (VGP) melanoma." (PMID 34452275, 2021).
prostate tumor (7 papers, 2011 to 2023). "Moreover, α-ionone, considered an OR51E2 antagonist, in fact promotes prostate tumor growth in vivo." (PMID 28032594, 2017).